APP (amyloid beta precursor protein)
Diseases named in the same sentence as APP in open-access papers (continued):
Sharing a sentence is not in itself a finding about the gene and the disease.
Alzheimer disease (continued). "At the early stage of Alzheimer's disease (AD), soluble amyloid β (Aβ) is produced when β‐secretase and γ‐secretase cleave amyloid precursor protein (APP)." (PMID 26733247, 2016). "Amyloid-β (Aβ), the major component of neuritic plaques in Alzheimer’s disease (AD), is derived from sequential proteolytic cleavage of amyloid protein precursor (APP) by secretases." (PMID 27532339, 2016). "Amyloid precursor protein (APP) is an integral membrane protein involved in the pathogenesis of Alzheimer’s disease (AD)." (PMID 27965537, 2016). "The neurotoxic amyloid beta (Aβ) peptide is a major component of senile plaques in Alzheimer's Disease (AD) and derives from its precursor the amyloid precursor protein (APP)." (PMID 28066176, 2016). "Mutations in the amyloid precursor protein (APP) gene and the aberrant cleavage of APP by γ-secretase are associated with Alzheimer’s disease (AD)." (PMID 27625790, 2016). "Cleavage of APP by the gamma secretase complex is instrumental in Alzheimer’s disease as documented by the identification of familial Alzheimer’s disease mutations in gamma secretase complex subunits." (PMID 26125944, 2015). "Best studied are the roles of γ-secretases in the processing of the amyloid precursor protein (APP) and the secretion of the neurotoxic amyloid β (Aβ) peptides in the context of Alzheimer disease." (PMID 25501811, 2015). "Alzheimer's disease can be caused by mutations in presenilin- (PS-) 1, PS2, or amyloid precursor protein (APP), as well as microtubule-associated protein tau." (PMID 26089911, 2015). "In this study, we report altered genomic mosaicism in single, sporadic Alzheimer's disease (AD) neurons characterized by increases in DNA content and amyloid precursor protein (APP) gene copy number." (PMID 25650802, 2015). "The Arc partner PS1 is a core component of the γ-secretase complex, which cleaves APP to generate the pathological amyloid β-peptides(Aβs) in Alzheimer's disease." (PMID 25748042, 2015). "In the present study, we applied two different experimental paradigms to investigate the contribution of the adaptive immune system to cerebral β-amyloid pathology in an established APP transgenic mouse model of Alzheimer’s disease." (PMID 26558367, 2015). "In line with this notion, progressive age-related amyloid plaque deposition was previously associated with a specific reduction of naturally occurring serum Aβ autoantibodies in the Tg2576 APP transgenic mouse model of Alzheimer’s disease." (PMID 26558367, 2015). "Beyond the pathology of Alzheimer’s disease, the members of the amyloid precursor protein (APP) family are essential for neuronal development and cell homeostasis in mammals." (PMID 25760599, 2015). "Amyloid precursor protein (APP) has been extensively studied for its role as the precursor of β-amyloid peptide (Aβ) in Alzheimer’s disease (AD)." (PMID 25904844, 2015). "Alzheimer’s disease (AD) is a progressive dementia characterized by altered processing of amyloid precursor protein (APP), formation of beta-amyloid plaques (Aβ), hyper-phosphorylated tau containing neurofibrillary tangles, and synaptic loss in the brain." (PMID 25992783, 2015). "Both NPTXR and VGF were found to be significantly different in a CSF of presymptomatic persons with familiar Alzheimer’s disease due to PSEN1 and APP mutations as compared to related non carriers by high resolution LC-MS." (PMID 26270474, 2015). "Amyloid precursor protein (APP) is widely recognized for playing a central role in Alzheimer's disease pathogenesis." (PMID 25591988, 2015). "Generation of β-amyloid (Aβ) peptide in Alzheimer's disease involves cleavage of amyloid precursor protein (APP) by γ-secretase, a protease known to cleave several substrates, including Notch." (PMID 26581893, 2015). "Attempts to treat Alzheimer's disease by targeting γ-secretase cleavage of APP into Aß have been unsuccessful, partially due to off-target effects." (PMID 26581893, 2015).
Alzheimer disease (continued). "In this study we demonstrate that the key player in Alzheimer's disease, APP, interacts with the PIKfyve complex and regulates the PIKfyve pathway in C. elegans, establishing an entirely novel role for APP." (PMID 26125944, 2015). "APP regulates numerous physiological functions in brain, but it is also cleaved to generate Aβ species involved in the pathology of the Alzheimer’s disease." (PMID 26202512, 2015). "Our results contribute to the elucidation of mechanisms involved in APP trafficking in Alzheimer disease." (PMID 25880931, 2015). "The amyloid precursor protein (APP) gene in the Alzheimer’s disease brain showed gradual hypomethylation in the promoter." (PMID 25637097, 2015). "The amyloid beta A4 precursor protein-binding, family B, member 2 (APBB2) gene encodes a protein that binds to amyloid beta precursor protein (APP), which is central to the pathogenesis of Alzheimer’s disease." (PMID 25887185, 2015). "Recently, the Ibero-American Alzheimer Disease Genetics Group Researchers analyzed the coding region and flanking sequences of APP, PSEN1, PSEN2, MAPT, and GRN by pooled-DNA exon sequencing in 167 clinical and five autopsy-confirmed, mainly EOAD cases." (PMID 25914626, 2015). "Fe65 has been relatively well-studied for APP signaling in Alzheimer’s disease but little is known about its functions in cancer cells." (PMID 26166158, 2015). "Amyloid precursor protein (APP) is best known for its involvement in the pathogenesis of Alzheimer's disease." (PMID 25695604, 2015). "The β-secretase, BACE1, cleaves APP to initiate generation of the β-amyloid peptide, Aβ, that comprises amyloid plaques in Alzheimer’s disease (AD)." (PMID 25567526, 2015). "The amyloid precursor protein APP is a class 1 transmembrane protein involved in the pathogenesis of Alzheimer’s Disease." (PMID 25778619, 2015). "In cell and animal models of Alzheimer's disease, increased Aβ processing from the amyloid precursor protein (APP) leads to Golgi fragmentation before cell death." (PMID 26594142, 2015). "A central event in Alzheimer’s disease is the accumulation of amyloid β (Aβ) peptides generated by the proteolytic cleavage of the amyloid precursor protein (APP)." (PMID 26618502, 2015). "Involvement of APP and Aβ fragments in Alzheimer's disease is well known (reviews:) but their role in the normal brain, particularly during the development, has been given less attention." (PMID 25889058, 2015). "In certain rat and APP transgenic mouse models of Alzheimer’s disease, for example, specific effector CD4+ T cells secreting IFN-γ, IL-17 or IL-22 were linked to increased neuroinflammation and exacerbation of disease progression." (PMID 26558367, 2015). "It was our goal to establish APP function which will provide insights into APP's implication in Alzheimer's disease." (PMID 26125944, 2015). "Cleaved APP products, Ab40 and Ab42, are important biomarkers for neurodegenerative diseases, in particular Alzheimer’s disease." (PMID 25898363, 2015). "Proteins related to the onset or progression of some CNS diseases such as APP (Alzheimer’s disease), PrPsc (prion disease), and α-synuclein (Parkinson’s disease), among others, have been found in the exosomal fraction of CSF-samples." (PMID 26834560, 2015). "APP overexpression leads to increased Aβ generation and Alzheimer’s disease in humans and altered neuronal migration and increased long term depression in mice." (PMID 26618502, 2015). "ABCA1also controls apoE lipidation, and has a role in Alzheimer's disease,including an impact on amyloid β (APP, P05067) deposition and clearance." (PMID 26650446, 2015). "This study investigated the effects of intervention with a combination of nutrients in the amyloid precursor protein-presenilin (APP-PSN) C57BL/6J double transgenic mouse model of Alzheimer’s disease (AD)." (PMID 26606074, 2015).
Alzheimer disease (continued). "The phosphodiesterase-5 inhibitor sildenafil reduces neuroinflammation in hippocampus and improves cognitive performance in APP/PS1 transgenic mice model of Alzheimer’s disease." (PMID 26511444, 2015). "While the Amyloid Precursor Protein (APP) plays a central role in Alzheimer’s disease, its cellular function still remains largely unclear." (PMID 26125944, 2015). "From Alzheimer’s disease, it is known that cleavage of APP via the β-secretase leads to the production of neurotoxic Aβ and the APP-intracellular domain (AICD)." (PMID 26426258, 2015). "In animal models of MS, Alzheimer's disease, and Parkinson's disease, KIF5 levels are significantly downregulated and are associated with NF, APP, and α-synuclein aggregations." (PMID 25639260, 2015). "The transmembrane protein Amyloid Precursor Protein (APP, NCBI: NM_000484) is the central player in Alzheimer’s disease, as patients with mutations in the APP gene develop a familial form of Alzheimer’s disease." (PMID 26125944, 2015). "Given that inactivation of the PIKfyve complex leads to neurodegeneration and that APP plays a key role in Alzheimer's disease this finding prompted us to investigate this interaction in more detail." (PMID 26125944, 2015). "β-site APP cleaving enzyme 1 (BACE1) initiates APP cleavage, which has been reported to be an inducer of tau pathology by altering proteasome functions in Alzheimer’s disease (AD)." (PMID 26778963, 2015). "In patient with Alzheimer’s disease (AD), deposition of amyloid-beta Aβ, a proteolytic cleavage of amyloid precursor protein (APP) by β-secretase/BACE1, forms senile plaque in the brain." (PMID 25773675, 2015). "The neurons from people with Alzheimer's disease contained more DNA—on average, hundreds of millions of DNA base pairs more—and more copies of the APP gene, with some neurons containing up to 12 copies." (PMID 25650802, 2015). "The intracellular transport and localization of amyloid precursor protein (APP) are critical determinants of APP processing and β-amyloid peptide production, thus crucially important for the pathophysiology of Alzheimer’s disease (AD)." (PMID 25904844, 2015). "Amyloid‐β (Aβ)‐peptide, the major constituent of the plaques that develop during Alzheimer's disease, is generated via the cleavage of Aβ precursor protein (APP) by β‐site APP‐cleaving enzyme (BACE)." (PMID 25712587, 2015). "The Amyloid Precursor Protein (APP) has been extensively studied for its role as the precursor of the β-amyloid protein (Aβ) in Alzheimer’s disease (AD)." (PMID 26690411, 2015). "The Amyloid Precursor Protein (APP) is a major actor of Alzheimer's disease (AD), a progressive neurodegenerative disorder in which the first symptom is the loss of episodic memory." (PMID 26274614, 2015). "Overexpression of the amyloid precursor protein (APP) and the hyperphosphorylation of the tau protein are vital in the understanding of the cause of Alzheimer’s disease (AD)." (PMID 25903151, 2015). "As a pathological peptide best known for its neurotoxicity in Alzheimer's disease (AD), Aβ is generated through the amyloidogenic pathway by cleaving the amyloid precursor protein (APP) into the intramembrane Aβ domain of 36–43 amino acids in length." (PMID 25698849, 2015). "Amyloid Precursor Protein (APP) is a key molecule in Alzheimer disease (AD) by the generation of its metabolites." (PMID 25880931, 2015). "More than 20 years ago the amyloid precursor protein (APP) was identified as the precursor protein of the Aβ peptide, the main component of senile plaques in brains affected by Alzheimer’s disease (AD)." (PMID 26834621, 2015). "Alzheimer's disease (AD) is characterized by an accumulation of Amyloid-β (Aβ), released by sequential proteolytic processing of the amyloid precursor protein (APP) by β - and γ-secretase." (PMID 26074811, 2015).
Alzheimer disease (continued). "We have recently shown that berberine, a compound in HLJDT, can significantly reduce the Aβ load in a transgenic Alzheimer’s disease model by regulating APP processing." (PMID 24671102, 2014). "The scientific scrutiny sustained by both APP and Notch results from their role in disease: aberrant γ-secretase cleavage of APP and Notch can lead to Alzheimer’s disease (AD) and cancer, respectively." (PMID 25610395, 2014). "N2a-SwedishAPP cells are widely used as a cellular model of Alzheimer’s disease, because they express a high level of APP and Aβ." (PMID 24671102, 2014). "Alzheimer’s disease pathology is closely connected to the processing of the amyloid precursor protein (APP) resulting in the formation of a variety of amyloid-beta (Aβ) peptides." (PMID 25031638, 2014). "A stronger and more functional interaction is one recently found between μ4 and a YXXØ-type, YX[FYL][FL]E motif contained in the cytosolic tail of the Alzheimer's disease amyloid precursor protein (APP)." (PMID 24498434, 2014). "This new technology will facilitate functional genomics studies of late-onset Alzheimer's disease, drug discovery efforts targeting APP and characterization of the physiological functions of APP and its proteolytic fragments." (PMID 24932508, 2014). "We developed a fluorescently tagged anti-Aβ RNA aptamer, β55, which binds amyloid plaques in both ex vivo human Alzheimer’s disease brain tissue and in vivo APP/PS1 transgenic mice." (PMID 24587111, 2014). "The amyloid precursor protein (APP) and amyloid-β (Aβ) peptide play central roles in the pathology and etiology of Alzheimer’s disease." (PMID 24361736, 2014). "We previously demonstrated that the amyloid precursor protein (APP) of Alzheimer disease regulates, at the epigenetic level, the transcription of the Egr1 gene." (PMID 24919190, 2014). "The sorting signals recognized by AP-4 have not been clearly defined until the discovery of the interaction with Alzheimer's disease APP (amyloid precursor protein)." (PMID 24975939, 2014). "In Alzheimer's disease, ROS affect the regulation of the processing enzymes of amyloid precursor protein (APP), which convert APP to the toxic Aβ1–42 oligomers." (PMID 24424024, 2014). "The current concept for Alzheimer's disease development involves the cleavage of amyloid precursor protein (APP) to amyloid beta (Aβ) peptide by BACE1 leading to the preliminary constituent of amyloid plaques in the brains of individuals with the disease." (PMID 25254246, 2014). "Alzheimer’s disease scores next with APP gene making the main contribution to the magnitude of the BC-ratio, being the first on the list of all genes." (PMID 25528190, 2014). "Work from our laboratory, in which the APP/PS1 Alzheimer’s disease mouse was crossed with a mouse that conditionally expressed IL-1β, demonstrated that four weeks of sustained inflammation led to decreased Aβ plaque deposition as opposed to enhanced pathology." (PMID 24889886, 2014). "Proteolytic processing of the amyloid precursor protein (APP) by the β- and γ-secretases releases the amyloid-β peptide (Aβ), which deposits in senile plaques and contributes to the etiology of Alzheimer's disease (AD)." (PMID 24466315, 2014). "In the pathogenesis of Alzheimer’s disease (AD) the homeostasis of amyloid precursor protein (APP) processing in the brain is impaired." (PMID 24608847, 2014). "ROS species upregulate Beta-Site APP cleavage enzyme 1 (BACE1), which cleaves amyloid precursor protein (APP) into amyloid Beta (Aβ), leading to increased production of the Aβ oligomer, the peptide widely accepted as the main pathogen in Alzheimer’s disease." (PMID 24363178, 2014). "The Swedish mutation of APP harboring double mutations at codons 595 and 596 (APP695 numbering) substituting Lys-Met to Asn-Leu is a predominant form of familial Alzheimer's disease." (PMID 24964199, 2014).
Alzheimer disease (continued). "Swedish double mutation (KM670/671NL) of amyloid precursor protein (APP) is reported to increase toxic amyloid β (Aβ) production via aberrant cleavage at the β-secretase site and thereby cause early-onset Alzheimer's disease (AD)." (PMID 24964199, 2014). "Disturbed α-synuclein (SNCA) and APP occurs in Parkinson's disease and Alzheimer's disease respectively, and expression of SNCA and APP was very highly correlated in Development (r = 0.67) and in Aging (r = 0.56)." (PMID 25329999, 2014). "The therapeutic system described in this report derives from basic studies of the role of APP signaling and proteolysis in plasticity, and the imbalance in this receptor proteolysis that reproducibly occurs in Alzheimer's disease." (PMID 25324467, 2014). "The β-amyloid precursor protein (APP) of Alzheimer's disease is a type I transmembrane protein with multiple spliced isoforms." (PMID 25218581, 2014). "Since its discovery, much of the research of the type 1 transmembrane protein β-amyloid precursor protein (APP) has focused on its proteolytic components, particularly the β-amyloid (Aβ) peptide that accumulates in Alzheimer’s disease." (PMID 25464026, 2014). "The amyloid precursor protein (APP) plays a central role in Alzheimer’s disease (AD) and has essential synapse promoting functions." (PMID 25520622, 2014). "Perturbation of lipid metabolism favours progression of Alzheimer disease, in which processing of Amyloid Precursor Protein (APP) has important implications." (PMID 23554170, 2013). "Amyloid precursor protein (APP) is a prototype RIP substrate that was analysed in great detail owing to its central function in the pathophysiology of Alzheimer’s disease." (PMID 24009667, 2013). "ICW have not been observed in cortex under physiological conditions, but have been observed occurring spontaneously under pathophysiological conditions in vivo in an APP/PS1 mouse model of Alzheimer's disease." (PMID 23847529, 2013). "The present study examined the effects of Gouqi (Lycium barbarum) on the learning and memory abilities of an APP/PS1 double transgenic mouse model of Alzheimer’s disease." (PMID 23737913, 2013). "Amyloid precursor protein (APP) mutant/MnSOD heterozygous knockout (APP19959/MnSOD+/-) mice show increased levels of Amyloid beta in Alzheimer's disease model." (PMID 24288463, 2013). "They include APP processing, cholesterol and lipoprotein function, complement and immune related genes, and oxidative stress, apoptosis and ubiquitin genes in Alzheimer's disease." (PMID 23533776, 2013). "As such, understanding the mechanisms that control APP processing and Aβ production has major relevance to Alzheimer's disease research." (PMID 23825109, 2013). "Amyloid precursor protein (APP) is a type 1 transmembrane protein that is considered to play a key role in Alzheimer's disease." (PMID 23662100, 2013). "The long noncoding RNAs (lncRNAs) within the mRNA sequences in Alzheimer's disease genes, namely, APP, APOE, PSEN1, and PSEN2, have been analyzed in terms of fractal dimension computation and correlation analysis." (PMID 23662159, 2013). "APP, a protein most widely studied for its role in Alzheimer disease, has recently been identified as a component of the TIP60 DNA repair complex, a complex that modifies histone acetylation at DNA double strand breaks." (PMID 23518061, 2013). "Less than 2% of AD cases are early-onset Alzheimer's disease (EOAD), which onsets prior to age 60 with genetic mutations in APP, presenilin 1, or presenilin 2 genes." (PMID 24367332, 2013). "Long noncoding RNA (lncRNA) within mRNA sequences of Alzheimer's disease genes, namely, APP, APOE, PSEN1, and PSEN2, has been analyzed using fractal dimension (FD) computation and correlation analysis." (PMID 23662159, 2013). "Secretion of amyloid precursor protein, APP, which is related to Alzheimer disease, is suppressed by interaction with the NatA complex." (PMID 24358196, 2013).